ENSG00000260464 (novel transcript)
Gene: Long non-coding RNA gene on chromosome 1 (93,847,174 to 93,848,939, forward strand). Ensembl gene ENSG00000260464.
Gene Ontology:
Molecular function: triplet codon-amino acid adaptor activity
Biological process: translation